LINC01257 (long independently transcribed non-coding RNA 1257)
Gene: Long non-coding RNA gene on chromosome 12 (131,165,000 to 131,238,936, forward strand). Ensembl gene ENSG00000204603.
Diseases named in the same sentence as LINC01257 in open-access papers:
LINC01257 is named in the same sentence as 4 diseases in open-access papers, as found by Europe PMC text mining. Sharing a sentence is not in itself a finding about the gene and the disease. The quoted sentences say what the papers report.
acute myeloid leukemia (1 paper, 2022). Acute myeloid leukemia (AML) is a group of neoplasms arising from precursor cells committed to the myeloid cell-line differentiation. "SiRNA targeting lncRNA LINC01257 was loaded into LNPs, and the expression of LINC01257 was decreased with the delivery of LNP-si-LINC01257 in the cell line model of pediatric acute myeloid leukemia (AML)." (PMID 35740920, 2022).
leukemia (1 paper, 2021). A malignant (clonal) hematologic disorder, involving hematopoietic stem cells and characterized by the presence of primitive or atypical myeloid or lymphoid cells in the bone marrow and the blood. "Furthermore, LINC01257 expression was absent in healthy progenitor CD34+ stem cells, MSCs and other subtypes of leukemia, highlighting the specificity of LINC01257 for AML and the value of its targeting as a precision medicine approach for this disease." (PMID 34683974, 2021).
LINC01257 also shares sentences with these, for which no sentence is quoted: acute lymphoblastic leukemia (1 paper); cancer (1).